CRP (C-reactive protein)
Diseases named in the same sentence as CRP in open-access papers (continued):
Sharing a sentence is not in itself a finding about the gene and the disease.
COVID-19 (continued). "Older patients with COVID-19 that died had worse laboratory findings compared to patients that survived in terms of lymphocyte number, ferritin, troponin, d-dimers, procalcitonin, CRP, and WBCs while some of these parameters have also been recognized by other studies." (PMID 36136824, 2022). "Pregnant women may suffer from asymptomatic COVID-19 and an increased leukocyte count, raised lymphopenia, and higher C-reactive protein (CRP) levels, requiring extracorporeal membranous oxygenation (ECMO) and invasive ventilation more than nonpregnant women do." (PMID 35456165, 2022). "At presentation, the COVID-19 patients in our cohort presented more ground glass features on a CT-scan and a lower leucocyte count, but they presented a higher lymphocyte count and higher c-reactive protein and lactate dehydrogenase values than the Influenza patients." (PMID 35740112, 2022). "However, a recent randomized controlled trial (RCT) found that tocilizumab does not improve clinical outcomes or decrease mortality at 28 days, although the findings of another RCT supports the use of tocilizumab for patients with moderate-to-severe COVID-19 and high c-reactive protein (CRP) levels." (PMID 36341409, 2022). "Finally, to identify independent prognostic factors of COVID-19-related lung damage severity, a multivariable logistic regression was performed, with age, sex, CRP, fibrinogen, D-dimer, thrombin time, uPAR serum level and PLAUR rs2302524 as independent variables." (PMID 36555850, 2022). "Moreover, analysis of patients admitted to the ICU showed an increase in CRP levels in the first seven days, suggesting that CRP levels may be correlated with lung injury and respiratory function in patients with COVID-19." (PMID 36560453, 2022). "However, many studies and meta-analyses have been performed that have proposed different biomarkers for poor prognosis for COVID-19, including C-reactive protein (CRP), albumin, procalcitonin, neutrophil-to-lymphocyte ratio, apolipoproteins, D-dimer, and ferritin." (PMID 36006278, 2022). "Importantly, another study has shown that BBR (900 mg/day, for 14 days) also could significantly reverse the changes in IL-6, TNF-α and C-reactive protein (CRP) levels in patients with severe COVID-19 with diarrhoea." (PMID 36147356, 2022). "Early in the COVID-19 pandemic, evidence suggested that SARS-CoV-2 interacts with the cardiovascular system, and several studies linked COVID-19 prognosis to cardiac biomarkers, including cTnI, CRP, D-dimer, procalcitonin (PCT), N-terminal pro-B-type natriuretic peptide (NT-proBNP), and CK-MB." (PMID 36080827, 2022). "COVID-19 patients presented decreased microbiota richness and diversity, when compared with the control group, with a predominance of opportunistic genera, such as Actinomyces, Erysipelatoclostridium, Rothia, Streptococcus, and Veillonella, which correlated with CRP and D-dimer levels." (PMID 36011823, 2022). "In this study, we aimed to explore whether lymphocyte–C-reactive protein ratio (LCR) can differentiate disease severity of coronavirus disease 2019 (COVID-19) patients and its value as an assistant screening tool for admission to hospital and intensive care unit (ICU)." (PMID 36248811, 2022). "Inflammation, reflected by cytokine storms and CRP in COVID-19 patients, could worsen the disease." (PMID 35967091, 2022). "Thus, markedly elevated CRP might act as a surrogate of excessive inflammation, leading to severe and critical illness, and even deaths in COVID-19." (PMID 35683357, 2022). "Furthermore, the authors reveal prior significant, unreported correlations between circulating DPP4 activity and CRP, D-dimer, IL-6 and peripheral blood lymphocyte count, which are all essential parameters currently used in the everyday clinical care of COVID-19 patients." (PMID 35195023, 2022).
COVID-19 (continued). "In this context, hyperferritinaemia, high CRP levels, and lymphopenia, along with some more sophisticated markers such as the soluble urokinase plasminogen activator receptor (suPAR) ≥ 6 ng/mL and SCOPE score ≥ 6, have already been associated with severity and survival of COVID-19 patients." (PMID 35458517, 2022). "The CRP levels were significantly increased in the COVID-19 patient group, whereas the lymphocyte count was notably decreased, which is consistent with previous reports that found that elevated CRP levels and lymphopenia were the main laboratory characteristics of COVID-19 patients." (PMID 35139909, 2022). "However, mean CRP levels were higher in patients with COVID-19." (PMID 34493032, 2022). "Likewise, hymecromone decreased the CRP and fibrinogen elevation of COVID-19 patients." (PMID 35304437, 2022). "Taken together, our findings suggest that admission values of lymphocyte counts, neutrophil-to-lymphocyte ratio and the levels of some inflammatory markers (IL8/CXCL8, MCP-1/CCL2, IL-10, and C-reactive protein) may be useful as COVID-19 outcome predictors during hospitalization." (PMID 36035415, 2022). "Derived laboratory biomarkers such as the de Ritis, CRP-to-albumin, LDH-to-hemoglobin, CRP-to-lymphocyte, and LDH-to-albumin ratios show significant association and discrimination with all-cause mortality in KTR with COVID-19, suggesting its potential risk stratification role." (PMID 36556433, 2022). "Indeed, diabetic patients have significantly higher serum inflammatory biomarkers including IL-6, C-reactive protein (CRP), D-dimer, serum ferritin and coagulation indices, resulting in a higher chance of an inflammatory storm and eventually worsening the outcome of COVID-19." (PMID 36143101, 2022). "In a previous study investigating COVID-19 survivors and deceased, the authors found significant differences between the two groups in terms of white blood cells, neutrophils, lymphocytes, monocytes, eosinophils, platelet counts, CRP, ferritin, and procalcitonin values from routine blood analysis." (PMID 35054342, 2022). "Additionally, positive correlations between admission IL-8/CXCL8, MCP-1/CCL2, IL-10, and C-reactive protein plasma levels and Δoxygen supply during hospitalization could predict COVID-19 worsening, and some studies partly corroborate these findings." (PMID 36035415, 2022). "Our data fits with this hypothesis, in that we show that ACE2 rs2285666 (CT + TT) SNPs are linked to alterations in inflammatory and other biomarkers (CRP, LDH, ferritin, D-dimer, lymphocytes and neutrophils), some of which are predictive criteria of a COVID-19 cytokine storm." (PMID 35996506, 2022). "This suggests that in critical COVID-19, strong elevation of IL-6 (e.g., > 100-120 pg/mL) and CRP levels (e.g., > 160-200 mg/L) could reflect augmented IL-6 cis-signalling in the attempt to exert homeostatic roles, while IL-10 further strengthens the predominance of SOCS3 over STAT3 signal." (PMID 35340805, 2022). "Associated risk factors may include gender (female sex), more than five early symptoms in the acute phase of COVID-19, early dyspnea, previous psychiatric disorders, and dysregulated specific biomarkers such as D-dimer, C-reactive protein (CRP), and lymphocyte count." (PMID 36560801, 2022). "The best predictive capability was observed for CRP (AUC 0.806 [0.734–0.878]); fibrinogen, D-dimer and uPAR serum levels showed comparable performances (AUC 0.76 [0.68–0.84], AUC 0.756 [0.677–0.835], AUC 0.738 [0.651–0.825]) in predicting COVID-19-related lung damage severity." (PMID 36555850, 2022). "Furthermore, a better understanding of the relationship between the inflammatory marker CRP and the QTc interval among individuals hospitalized for COVID-19 will add to the growing body of the literature on the role of inflammation in acquired prolongation of QTc interval." (PMID 35811700, 2022).
COVID-19 (continued). "Upon admission, the COVID-19 patients presented significantly more ground glass features on the CT-scan and a lower leucocyte count, but they presented a higher lymphocyte count and higher c-reactive protein and lactate dehydrogenase values than the Influenza patients." (PMID 35740112, 2022). "Moreover, it is known that serum CRP levels in patients with COVID-19 may be affected by the presence of bacterial co-infections." (PMID 36560453, 2022). "In addition to IL-6, CRP is a significant marker of COVID-19 inflammation." (PMID 35237386, 2022). "Patients with Coronavirus Disease-2019 (COVID-19) are characterised by abnormal levels of inflammatory biomarkers such as C-reactive protein (CRP), ferritin, fibrinogen and especially elevated level of D-dimer which indicates need for critical care and may lead to death." (PMID 36705193, 2022). "A regression analysis showed that C-reactive protein was significantly associated with worsening conditions in patients with non-severe COVID-19, with an area under the curve of 0.844 (confidence interval of 95%, 0.761–0.926) and an optimal threshold value of 26.9 mg/L." (PMID 35564749, 2022). "Therefore, the objective of this study was to analyse whether the analytical standards of serum ferritin, glucose, D-dimer, and C-reactive protein are altered in asymptomatic patients, as occurs in symptomatic patients infected with COVID-19." (PMID 35564749, 2022). "In this study, we unraveled that older age and higher levels of laboratory test indexes such as CRP, LDH, and glucose, and lower levels of laboratory findings such as lymphocytes and albumin on admission were associated with higher probabilities of critical illness COVID-19." (PMID 35677769, 2022). "Furthermore, increased CRP levels explained part of the elevated risk of COVID-19-related mortality with age, specifically in the absence of obesity and impaired metabolic health." (PMID 35646955, 2022). "Our study confirms these positive findings as the authors hypothesized that lower CRP, the main outcome of our meta-analysis, might be one of the reasons Omega-3 decreased COVID-19 physical symptoms as the improvements in inflammatory parameters are correlated to the clinical changes." (PMID 36064554, 2022). "Furthermore, mild elevations in the levels of inflammatory markers such as C-reactive protein (CRP), procalcitonin (PCT), and D-dimer, a biomarker associated with COVID-19 disease severity, returned to the normal range at follow-up, as well as those of other serological markers of the patients." (PMID 35062289, 2022). "A prospective cohort study of 89 patients showed that high concentrations of IL-6 followed by CRP could predict respiratory failure and the need for mechanical ventilation in patients admitted with COVID-19 with significant time difference between CRP and IL-6 in favour of IL-6." (PMID 35500008, 2022). "Therefore, our aim was to investigate and compare the prognostic impacts of CRP, PCT NLR, PLR, LMR, and SII biomarkers in laboratory-confirmed COVID-19 cases as well as to explore the most useful diagnostic biomarkers and optimal cut-off values in COVID-19 patients to predict in-hospital mortality." (PMID 35453906, 2022). "Anaemia, renal impairment and elevated LDH were more frequent in patients with any AD while elevated CRP and LDH were more frequent in patients with severe rheumatologic AD both of which have been shown to associate with increased mortality in patients with COVID-19." (PMID 35377457, 2022). "Thus, this significantly higher proportion of Roma patients with severe COVID-19 that showed high levels of IL-6 at admission can explain why these patients also had continuously elevated inflammatory markers at admission, such as CRP and ESR." (PMID 36431254, 2022). "Indeed, inflammatory indices, including LDH, CRP and IL-6 may help to identify cases with dismal prognoses in COVID-19 subjects and perform a prompt intervention in order to improve outcomes." (PMID 36619546, 2022).
COVID-19 (continued). "However, further investigation is needed to evaluate if both markers may be used in conjunction with other predictive markers for COVID-19 such as C-reactive protein (CRP), IL-6, procalcitonin (PCT), D-dimer and serum ferritin." (PMID 36615083, 2022). "Therefore, increase in IL-6 and CRP might be helpful to distinguish the early stage (mild to moderate) of COVID-19 patients." (PMID 36219652, 2022). "In conclusion, derived laboratory biomarkers such as the De Ritis ratio, CRP-to-albumin ratio, LDH-to-hemoglobin ratio, CRP-to-lymphocyte ratio, and LDH-to-albumin ratio show significant association with all-cause mortality in KTR with COVID-19, suggesting their potential risk stratification role." (PMID 36556433, 2022). "Most of the chosen markers change in abundance between healthy and COVID-19-infected individuals, and further follow their respective trend with increasing treatment escalation level, such as peptides derived from the acute-phase proteins CRP and AHSG, or the innate-immune-response protein PGLYRP2." (PMID 35702332, 2022). "Laboratory biomarkers, such as C-reactive protein (CRP), ferritin, D-dimer, cardiac troponin (cTn), NT-proBNP, lymphopenia, neutropenia, and, if available, circulating IL-6 levels have been associated with MIS in Stages 2–3 and also with poor outcomes of COVID-19." (PMID 36430430, 2022). "Patients hospitalized with COVID-19 experience an increase in blood aminotransferase (AST) levels that is favorably correlated with alanine aminotransferase (ALT) levels but not with markers of muscle breakdown such as creatine kinase (CK) or systemic inflammation (C reactive protein and ferritin)." (PMID 35928369, 2022). "An underlying infection as a trigger for aHUS could be excluded in all patients, as infection parameters were low (CRP <1-7 mg/L, leukocyte count 3.6-10.3x109/L) and viral (among others Influenza A/B and COVID-19) and bacterial (including STEC) serological diagnostics were negative." (PMID 36531998, 2022). "Interestingly, in COVID-19 cohort, sEng levels correlated with CRP levels." (PMID 36117974, 2022). "Unfortunately, we were unable to obtain biochemical measures of inflammation (C-reactive protein and interleukin-6) and other markers (fibroblast growth factor 23 and prealbumin) in the majority of study participants at all time-points due to the COVID-19 pandemic." (PMID 35810296, 2022). "Furthermore, the short duration between the finding of COVID-19 positivity and the blood draw (1–3 days) suggests that the blood draw may have been performed before an increase in the CRP level; therefore, the CRP level may have been low." (PMID 36316726, 2022). "This cytokine release syndrome may contribute to many of the clinical and laboratory findings reported in severe COVID-19: cytopenias, coagulopathy, hyperferritinemia and other acute-phase reactants (e.g., CRP, D-dimer) increase, endothelial damage and vascular permeability." (PMID 35353232, 2022). "Based on the results of our study, we believe that the levels of D-dimer, CRP, ferritin, and LDH might help identify those COVID-19 patients at greater risk of developing a worse prognosis earlier, even in individuals showing no severe symptoms and signs in the emergency room." (PMID 35054342, 2022). "Additionally, cytokine storms have been suggested to play essential roles in COVID-19 disease severity, and elevated CRP may indicate a more severe form of COVID-19." (PMID 35154932, 2022). "In addition to reductions in NP SARS-CoV-2 RNA levels, we found biological evidence of activity of bamlanivimab against COVID-19 progression, with greater reductions in inflammatory biomarker levels (CRP, ferritin, and fibrinogen) with bamlanivimab compared to placebo." (PMID 35995785, 2022).
COVID-19 (continued). "Also, the Chinese COVID-19 diagnosis and treatment plan (trial version 8) recommended dropping lymphocytes, rising inflammatory factors (e.g., IL-6, CRP), increasing LDH and rapidly progressive pulmonary changes are the predictive factors for severe and critical COVID-19." (PMID 33588779, 2021). "A significant linear correlation between hs-CRP and systolic blood pressure has been observed in the present study, suggesting HTN associated pro- inflammatory state might drives cardiac injury that worsens the prognosis of patients with COVID-19." (PMID 34789776, 2021). "The CRP provided by the increased plasma levels secondary to elevated CRP hepatocyte synthesis and the local production by epithelial cells of the human respiratory tract can facilitate the antimicrobial activity of bacteria complicating any RNA coronavirus infection such as COVID-19." (PMID 34630377, 2021). "The use of CRP as a biomarker in COVID-19 may present a quick and accessible tool in clinical management, trigger longer periods of enhanced observation, provide information around likely disease progression and assist with early therapeutic, ventilation and palliative care discussions." (PMID 33683344, 2021). "Finally, we analyzed the correlation between the indicators related to the reduction of Ca2+ (including serum Ca2+, PCT and calcitonin), coagulation function-related indicators (including D-dimer and PFDP), and inflammation indicators (ESR, CRP, and IL-6) in COVID-19 patients." (PMID 34222271, 2021). "Therefore, the CRP/Alb ratio is easy to obtain and cheap, changes early with the progression of the disease, and can be used as an effective index for the early detection of disease progression in patients with severe COVID-19." (PMID 34900028, 2021). "Moreover, antidepressant use has been associated with a reduced risk of intubation or death in hospitalized patients with COVID-19 because the inhibition of ASM decreases pro-inflammatory mediators such as IL-2, IL-6, IL-7, IL-10, TNF-α, C-reactive protein (CRP), and D-dimer." (PMID 34579284, 2021). "However, in response to interaction with circulating virus through molecules such as C5a and CRP, this mechanism may be hijacked by the virus for its replication advantage leading to tissue damage and fatal sequelae observed in COVID-19." (PMID 34691068, 2021). "Among patients with COVID-19, fever, fatigue, and dry cough were the major presenting symptoms; hypertension, chronic heart failure, and diabetes were the leading comorbidities, and lymphopenia with elevated CRP or lactate levels were the main laboratory findings." (PMID 33869276, 2021). "Exceeding the CRP threshold may lead to multiple organ failure in COVID-19 patients." (PMID 34778296, 2021). "Moreover, CRP was correlated to the acute lung injury in COVID-19 patients." (PMID 34195215, 2021). "Interestingly, baseline lymphocytes, LDH, and CRP, which are all independently associated with COVID-19 severity, did not predict weaning failure in our study." (PMID 34683115, 2021). "In COVID-19, metabolic status changes, namely, the increased levels of circulating glucose and FFA, high levels of oxidative stress, and SIR (including IL-6, CRP), that are characteristic of pathologies associated with insulin resistance and correlates with the severity of the disease, may occur." (PMID 34299201, 2021). "In conclusion, CHANeL prediction models based on serial measurements of CRP, ANC, and ALC during first 3 days of hospitalization, along with age and hypertension, provide an accurate estimate of the risk of supplement oxygen requirement among hospitalized patients with COVID-19." (PMID 34158545, 2021). "Similarly, the elevation of CRP levels was observed in the majority of COVID-19 patients." (PMID 34555027, 2021).